IFNG (interferon gamma)
Diseases named in the same sentence as IFNG in open-access papers (continued):
Sharing a sentence is not in itself a finding about the gene and the disease.
tumor (continued). "An example of this is the suggestion that Gal-3 can trap IFNγ in the tumor stroma thus preventing the recruitment and activation of cytotoxic T cells (CTL) while blockade of Gal-3 causes an increase in cytokine activity which increased the recruitment of CTLs into the tumor." (PMID 37701441, 2023). "Indeed, the capacity of NK cells to produce anti-tumor acting IFNγ upon PMA+ionomycin stimulation was similar in cells from CTCL and healthy skin." (PMID 37691935, 2023). "In addition, we observed a significant correlation between the level of tumor infiltration of IFNγ-producing ɣδ T cells and tumor growth in all three tumor models, confirming their pivotal role in inulin-mediated anti-tumor effects." (PMID 36875124, 2023). "Antibody-mediated bridging between FcγRIIIA/FcγRIIA on NK cells/phagocytes and target antigen on the tumor cells can trigger the release of IFNγ, TNFα, IL6, and MCP-1 during the ADCC reaction and NK cell–secreted IFNγ and TNFα were shown to potentiate the NK-mediated target cell lysis." (PMID 37067909, 2023). "Similarly, the hypoxic nature of the TIME drives upregulation of LDHA in CD8+ tumor-infiltrating lymphocytes (TILs), leading to excess intracellular lactic acid, which then inhibits IFNg and granzyme B production and T cell expansion." (PMID 37842241, 2023). "Liposomal nanoparticles with IL-2 and TGF β can mediate macrophage and NK cell homing and infiltration in the tumor site, and nanocomposite containing IFNγ or IL-2 can facilitate the conversion of immunosuppressive TME to more immunoresponsive environment enhancing NK tumor recognition and killing." (PMID 36834917, 2023). "Based on complementary RNA data, nCRT increased IFNγ expression in tumor cells, perhaps as a result of the increased influx of cytotoxic T lymphocytes to balance the immune response by inducing tumor cells to express checkpoint molecules like PD-L1 and Indoleamine 2,3-Dioxygenase (IDO)." (PMID 37006319, 2023). "In addition to cytotoxicity, γδ T cells play a critical role in protective immune responses against tumor development by providing an early source of the proinflammatory cytokine IFNγ." (PMID 37139603, 2023). "Tumor transcript analysis using interferon regulatory factor 1 (IRF1) expression as a readout of IFNγ signaling suggested there may be a marginal disruption of this pathway." (PMID 38130991, 2023). "Notably, in contrast to cytolytic granules, which act only locally at the T cell-tumor cell interface, IFNγ spreads into the tumor microenvironment." (PMID 37965314, 2023). "High levels of expression of GZMB and FASL (encoding Granzyme B and Fas ligand) but low levels of IFNG and TNF (encoding Interferon-γ and TNF-α) in these exhausted-like T cells are suggestive of an altered cytotoxic profile but remaining capacity for tumor cell killing." (PMID 36609566, 2023). "Indeed, CD47 KO in A549 cells attenuated IFNγ-stimulated invasion and migration in vitro and tumor metastasis in mice." (PMID 37958404, 2023). "Compared with proliferating cells, senescent cells upregulate the IFNγ receptor, become hypersensitized to microenvironmental IFNγ, and more robustly induce the antigen-presenting machinery-effects also recapitulated in human tumor cells undergoing therapy-induced senescence." (PMID 36302222, 2023). "In a model of sporadic CRC, genetic IL-13 deficiency significantly reduced tumour burden, and adoptive transfer of IL-13+ ILC2s compared to IL-13– ILC2s led to enhanced MDSC activation and downstream suppression of anti-tumoural IFNγ+ CD8+ T cells and Th1 cells." (PMID 37455828, 2023). "Initially, T cells may exhibit anti-tumor activity, particularly Th1 cells producing interferon gamma (IFN-γ), and influence disease development." (PMID 37048814, 2023). "Moreover, their anti-tumor activity was further confirmed by the presence of granzyme B+ and IFNγ+ staining in CD8+ T cells from responders." (PMID 36707872, 2023).
tumor (continued). "Along with our observation that TAG72-dCH2(28tm)BBz CAR T cells secreted the highest levels of IFNγ in our studies, we hypothesized that IFNγ signaling contributed to the superior anti-tumor activity of TAG72-dCH2(28tm)BBz CAR T cells." (PMID 37550294, 2023). "These associations may also reflect the suppression of local anti-tumour inflammatory response in necrotic tumours, considering that CXCL10 and IFNG are regarded as important cytokines in the antitumorigenic T helper type 1 response." (PMID 37031328, 2023). "Other work has described an indirect role of CAR-T produced IFNγ in enhancing anti-tumor immunity." (PMID 38052854, 2023). "Consistently, in a mouse model of sarcoma, the tumor glucose consumption dampened T cell mammalian target of rapamycin complex 1 (mTORC1) activity, their capacity to do glycolysis and to produce IFNγ, lowering adaptive anti-tumor activity in spite of the high antigenicity of the cancer cells." (PMID 37180110, 2023). "IFNγ is the main effector cytokine of type 1 immune response and is established as the prototypical anti-tumoural cytokine with critical roles in anti-cancer immunity and tumour rejection." (PMID 37455828, 2023). "However, after continuous exposure and recognition of tumor antigens, tumor-specific effector T cells induce increased expression of PD-1 and secrete interferon-gamma (IFN-γ), a chemical signal that induces the expression of B7 H1 (PD-L1) in neoplastic cells." (PMID 37222345, 2023). "F. nucleatum could induce PD-L8 expression by activating STING signaling during PD-L1 blockade therapy and increase the interferon-gamma (IFN-γ) CD1 tumor-infiltrating lymphocytes (TILs), which increases tumor sensitivity to PD-L1 blockade." (PMID 38156313, 2023). "However, as expected, the culture of tumor cells in the presence of IFNγ resulted in a marked upregulation of Qa‐1b surface expression." (PMID 37782273, 2023). "Importantly, anti-IFNγ combined with cisplatin treatment increased the perfusion of lectin into the tumour vessels while reducing the leakage of dextran into the tumour vessels." (PMID 37056922, 2023). "Our data highlight the dual pro- and anti-tumor functions IFNγ exerts on T cells." (PMID 36658158, 2023). "COMT also interacts with the pro-inflammatory cytokine tumor necrosis factor and with the tumor growth factor β1 (TGFβ1) that can modulate expression/activation of other growth factors, such as interferon gamma and tumor necrosis factor alpha, and is frequently up-regulated in tumor cells." (PMID 36827167, 2023). "Using this model we could describe all the experimental data, which led us to conclude that IFNG-mediated tumor cell-cycle arrest, together with killing of tumor cells by CTLs, was sufficient mechanism to account for the experimental data." (PMID 37182110, 2023). "In order to obtain preliminary evidence of the clinical suitability of emapalumab to manage CAR-T cell toxicities, we first evaluated whether neutralization of the IFNγ axis affects the cytotoxic activity CAR-T cells against CD19+ tumor cells." (PMID 37296093, 2023). "Surprisingly, when we challenged IFNγR1−/− mice with wild-type tumors, we discovered that these mice could still largely control their tumors, suggesting that tumor sensing of IFNγ was now controlling tumor growth." (PMID 36881506, 2023). "Notably, inflammatory responses as well as interferon alpha response and interferon gamma response pathways were significantly suppressed in epithelial cells in brain metastases compared to tumor tissues." (PMID 37715019, 2023). "In view of the observation that neutralising IFNγ blocked the destruction of tumour blood vessels by cisplatin, we speculated that neutralising IFNγ might promote drug delivery." (PMID 37056922, 2023). "One such potential pathway is IFNγ-mediated upregulation of SOCS1 in tumor cells." (PMID 37711623, 2023).
tumor (continued). "A total 40 μg of GSDMBNT mRNA@LNPs was intratumorally injected into 4T1 tumors and then the concentrations of inflammatory cytokines including tumor necrosis factor-alpha (TNF-α) and interferon-gamma (IFN-γ) in tumor tissue or serum were assayed by ELISA after 6, 24, or 72 h, separately." (PMID 37454146, 2023). "Given that IL-12 is known to increase the expression of PD-L1 on tumor cells via IFNγ,51 we sought to investigate whether intratumoral injections of mRNAs encoding IL-12-taFv1 and IL-12 would result in the upregulation of PD-L1 expression on tumor cells." (PMID 37650116, 2023). "This is because several hybrid cells escape the tumor, thereby no longer inhibiting IFNγ production of intratumoral T cells, and causing the remaining epithelial cells to reside close to the IFNγ-rich tumor center." (PMID 37638024, 2023). "We theorized that Ptpn2 inhibition might sensitize tumor cells to ICI treatment by increasing IFNγ signaling." (PMID 36968224, 2023). "However, only Tex showed a decreased capacity to degranulate (CD107a exposure upon restimulation), produce the inflammatory cytokines IFNγ and TNFα, and kill tumor cells." (PMID 36732507, 2023). "Dysregulated interferon-gamma response pathway inhibits immune checkpoint responses in tumor cells." (PMID 38260829, 2023). "A higher level of CD8+ T cells and interferon gamma were also found among the mice group with better survival receiving neoadjuvant blockade.They also observed presence of tumor-directed CD8+ T cells up to 170 days out of tumor inoculation in the neoadjuvant group." (PMID 37249833, 2023). "Overall, our analysis suggests that the pulse of IFNG production remains brief despite CTLs still being present within the tumor and might be due to development of an exhausted phenotype among the transferred CTLs." (PMID 37182110, 2023). "Indeed, the persistent duration of IFNG signaling in tumor cells has been reported to regulate the resistance to ICIs by the activation of multiple inhibitory pathways." (PMID 36980174, 2023). "After OV treatment, IFNγ increases in the tumor interstitial fluid in both MEERvvR and MEERvvS; however, in accordance with a more fragile phenotype, only MEERvvS infiltrating Treg cells have increased IFNγ signaling and consequent IFNγ production, consistent with previous data." (PMID 37552475, 2023). "In line with this hypothesis, IFNγ is required for successful tumor rejection by dual blockade of TGFβ and PD-L1, and knocking out IFNγ receptor in tumor cells leads to decreased complete response to dual PD-L1 TGFβ blockade." (PMID 37543621, 2023). "Interferon-gamma-induced signaling occurred in many types of immune cells, such as type I helper T cells, cytotoxic T cells (CTLs), and NK cells, while interferon-γ-dependent immunotherapy acted primarily through the anti-tumor mechanism." (PMID 36899891, 2023). "As such, this may be a common thread of immunotherapy; increasing Treg cell sensitivity to cytokines like IFNγ helps drive a more complete anti-tumor immune response." (PMID 37552475, 2023). "Interestingly, NK cells were upregulated in tumours derived from chronic IFNγ-pre-treated YUMM2.1 cells, again reversed upon PARP14 knockdown, but there was no dysregulation in gamma-delta T cells." (PMID 37752135, 2023). "We show that FAK deletion in cancer cells derived from mouse KPC tumours reprogrammes the cellular response to IFNγ, increasing both antigen diversity through activation of the immunoproteasome and surface presentation through upregulation of MHC-I to promote immunosurveillance." (PMID 36977556, 2023). "A possible mechanism is that circulating lymphocytes may promote cytotoxic cell death to exert anti-tumor effect by secreting cytokines such as interferon-gamma and tumor necrosis factor-alpha." (PMID 36969019, 2023).
tumor (continued). "In addition, high-risk group had significantly elevated levels in glycolysis and recognition of tumor cells, but lower levels in IFNg response, inhibitor cells (Tregs), innate immunity, priming and activation of immunology and T cells." (PMID 37735483, 2023). "Indeed, antiproliferative effects of IFNG are mediated by inhibitors of cyclin-dependent kinases, which result in arrest of tumor cells at the G1 phase of the cell cycle, as shown in a variety of cell lines." (PMID 37182110, 2023). "Consistent with our previous work on this topic, our model predicted that the cytotoxic effects of CTLs were small and that cytostatic effects of IFNG were responsible for almost all of the observed difference in tumor growth between CTL-treated versus untreated tumors." (PMID 37182110, 2023). "To block direct presentation, we used CRISPR to delete B2M from the cancer cells to generate cancer cells that were unable to express MHCI even following IFNg stimulation, and these cells were unable to directly present antigen to tumor-specific CD8 T cells in vitro (Fig. 2cii)." (PMID 37072485, 2023). "In the present study, the negative correlation between high IFNγ expression and OS and ICI response may be attributed to the pro-tumor immune effects of the IFNγ pathway." (PMID 38026978, 2023). "However, a different study reported a link between tumor PD-L1 and plasma PD-L1/PD-1 levels and plasma interferon-gamma (IFN-γ) or interleukin-10 (IL-10)." (PMID 38187399, 2023). "In addition, the intrinsic IFN type I (IFNα and IFNγ) signaling pathway is essential for the cytotoxic T lymphocyte (CTL) effector function in tumor suppression." (PMID 36982677, 2023). "Given that Ptpn2 sgRNA depletion is only seen in the in vitro screen condition in which anti-mCD19 CAR-T cells were added, these data suggest that mCD19-mediated release of IFNγ from anti-mCD19 CAR-T cells can exert anti-tumor activity in our in vitro screen conditions." (PMID 38052854, 2023). "This APC-like behaviour of neutrophils has been observed in NSCL patients, where a subset of immature neutrophils (CD11b+ CD15hi CD10– CD16int/low) acquired the expression of MHCII and CD86 in response to GM-CSF and IFNγ and triggered a T cell-mediated anti-tumour response." (PMID 37180120, 2023). "Notably, NK cells can kill tumor cells directly as well as by activating DCs through IFNγ production." (PMID 36851984, 2023). "Notably, PDL1 and CTLA4 Abs increased the proliferation of lymphocytes, tumor cell death and the synthesis of pro-inflammatory IFNγ at the expense of anti-inflammatory IL10 in triple-negative samples as well." (PMID 37686465, 2023). "Further analysis of the tumor lysates indicated that V-Navo@gel could elevate pro-inflammation cytokines (IL12 and IFNγ) and granzyme B, the marker of activated T cells, at the tumor site, indicating the elevated anti-tumor immune responses against tumors." (PMID 37296221, 2023). "Given its ability to penetrate deep inside the tumor, modulating the IFNγ-ERK cell death pathway described here could be an effective strategy for controlling the tumor burden." (PMID 37803324, 2023). "Consequently, epithelial tumor cells have on average a 7.0% lower IFNγ exposure in heterogeneous versus homogeneous tumors with PD-L1-mediated IFNγ inhibition." (PMID 37638024, 2023). "Therefore, the selective delivery of IFNγ to the tumor site can promote an inflammatory T-cell generation and trafficking mediated by IP-10 release." (PMID 36839699, 2023). "More importantly, there is evidence that loss-of-function mutations at JAK1 promote a lack of response to interferon gamma, leading to resistance to immunotherapy in tumor cells." (PMID 36675550, 2023). "Thus, tumor cells with intrinsic IFNγ activity occur in a tumor microenvironment with a paucity of activated CD8+ effector T cells." (PMID 36934113, 2023). "In contrast, IFNγ has pro-tumor immune effects and plays a dual role in the tumor microenvironment." (PMID 38026978, 2023).
tumor (continued). "In addition, pharmacological inhibitor (GSK’547) of RIP1 was demonstrated to alter the phenotype of TAMs from immunosuppressive to immunogenic (MHCIIhiTNFα+IFNγ+) with significant reduction in tumor burden and metastasis." (PMID 37488598, 2023). "On the other hand, treatment of PDX mice with both p402 mAb and p40 mAb led to a significant decrease in CA19-9 and a marked increase in IFNγ in tumor tissues, indicating an improvement in disease prognosis in comparison to either untreated control or IgG-treated PDX mice." (PMID 38136341, 2023). "We also examined tumor expression of a number of IFNγ response genes by qRT-PCR analysis." (PMID 36968224, 2023). "However, the enhanced intratumoral accumulation of Foxp3UP CD8 T cells counteracted the negative effect of FoxP3 overexpression on cytokine production and resulted in a higher number of IFNγ+ TNFα+ CD8 T cells within the tumor." (PMID 36045586, 2023). "Interestingly, the ratio of TNFα+ CD4+ to IL-17A+ CD4+ T cells was also skewed towards more IL-17A+ CD4+ T cells in the tumor tissues versus STM while the ratios of IFNγ+ CD4+ and TNF+ CD4+ T cells showed a small change towards more TNFα." (PMID 38074634, 2023). "With the biomarker assessment module of the TIDE website, we evaluated the accuracy of PES1 in five ICB HNSCC cohorts and compared it with other published biomarkers associated with tumor immune evasion, including CD274 (PD‐L1), MSI Score, CD8, Merck18, and IFNG." (PMID 37076985, 2023). "Notably, oncolytic viral therapy can not only kill tumor cells, but also increase cytokines such as interferon gamma and interleukins, which are present in the TME, resulting in an improved innate immunologic response to tumor cells." (PMID 37465684, 2023). "For instance, the researcher transduced the IL-12 gene into macrophage structure with lentiviral approaches and showed these macrophages could experiment with better infiltration and reduce the tumor sizes and IFNγ production." (PMID 38017494, 2023). "In addition to active cell migration to form stable conjugations with target cells, CAR-T cells can produce various cytokines, such as TNFα and IFNγ, in the tumor microenvironment." (PMID 37388744, 2023). "It is possible that elimination of solid tumors may require T cells with a unique phenotype that are more highly activated, produces more inflammatory cytokines such as IFNγ and are more efficiently recruited to tumor beds." (PMID 37388744, 2023). "Tumor tissues with high DSE expression showed higher levels of IFNG, GZMB, and TNF expression." (PMID 37833287, 2023). "IFNG enhances MHC-I thereby favoring neo-antigen presentation of tumor cells." (PMID 37138100, 2023). "Meanwhile, preclinical research indicates that changes in the immune microenvironment may assist with surgical timing, and the effects on surgery caused by prolonging the interval may be related to the proportion of tumor-specific T cells and IFNγ production." (PMID 36761954, 2023). "IFNγ has long been recognised as a key mediator of tumour immunity and angiostasis." (PMID 37056922, 2023). "For instance, IFNγ may contribute to cancer immune evasion by augmenting the expression of PD-L1 by tumor cells and dampening the anti-tumor activity of exhausted T-cells expressing PD-1 receptors." (PMID 36839699, 2023). "However, IFNγ also has important tumor‐promoting functions that include the induced PD‐L1 and IL‐8 expression resulting in increased cancer cell proliferation and immune escape, but the mechanisms are much less understood." (PMID 37151134, 2023). "However, these predictions are contradicted by experimental findings showing that IFNγ produced by activated CD8+ T cells diffuses substantially from the site of tumor cell-T cell interaction." (PMID 37638024, 2023). "TRP restoration, too, was able to revert the anti-tumor effect of either T cells or IFNγ treatment." (PMID 36812891, 2023).